IL10 (interleukin 10)
Diseases named in the same sentence as IL10 in open-access papers (continued):
Sharing a sentence is not in itself a finding about the gene and the disease.
enteritis (continued). "Recent studies have shown that IL-1β and TNF-α can be proinflammatory cytokines in IBD, whereas IL-10 has been demonstrated to play a vital role in the control of inflammation and prevention of enteritis." (PMID 31341536, 2019). "While both control and IL-10-deficient C57BL/6 mice can be colonized by C. jejuni, only C57BL/6 IL-10−/− mice develop enteritis." (PMID 24987092, 2014). "Regarding the impact of inflammatory changes in small intestine, a previous study has described that IL-10−/− mice can develop enteritis in conventional conditions." (PMID 22400037, 2012). "Quantitative PCR analysis showed that CGA suppressed the expression of pro-inflammatory factors including interferon-γ (Ifn-γ), interleukin-7 (Il-7), tumor necrosis factor-α (Tnf-α), and upregulated the anti-inflammatory cytokines interleukin-10 (Il-10) in LPS-induced enteritis mice." (PMID 41788896, 2026). "CB increases IL-10 expression in mice and in broilers under enteritis conditions." (PMID 36674973, 2023). "In contrast, Il-10 and Tgf-β are key factors in preventing enteritis development." (PMID 38143747, 2023). "Furthermore, IL-10 levels were much lower in enteritis mice than in the normal group, while TNF-α, IL-1β, and IL-6 levels were dramatically enhanced after DSS administration." (PMID 37375702, 2023). "We could show that, like in OVA-induced enteritis, an increase in MC numbers takes place in the duodenum and colon of IL-10−/− mice." (PMID 35163137, 2022). "Interestingly, after 6 days post-infection, Il10−/− mice infected with chicken-transmitted Cj-P1 showed clinical sign of enteritis." (PMID 33257743, 2020). "Irrespective of the C. jejuni strain, however, infected gnotobiotic IL-10−/− mice developed comparable clinical symptoms of enteritis over time in the presented study, which was contrasting the less pronounced immunopathological outcome in the intestinal tract." (PMID 24587249, 2014). "IL-10−/− mice have been used to study C. jejuni colonization and enteritis before." (PMID 22808254, 2012). "Using IL-10−/− mice housed in specific pathogen free (SPF) conditions, Mansfield and colleagues demonstrated that enteritis developed in ∼50–80% of C. jejuni (NCTC 11168) colonized IL-10−/− mice after more than 28 days of infection depending on the genetic background." (PMID 19841748, 2009). "Furthermore, the observation that there are differences between C. jejuni strains in the ability to produce enteritis in C57BL/6 IL-10-/- mice shows that the development of severe disease cannot be solely attributed to the immune alterations of the mice." (PMID 19296832, 2009). "Additionally, IL-10 knockout mice spontaneously develop enteritis." (PMID 40756994, 2025). "Moreover, the level of IL-10 in people with enteritis was increased, which could effectively inhibit inflammation." (PMID 38739270, 2024). "Following DSS-induced enteritis, there was a significant increase in the protein levels of CXCL10 and TNF-α, coupled with a notable decrease in IL10 and CCL17." (PMID 38774206, 2024). "Lack of IL-10 is associated with the occurrence of autoimmune and inflammatory diseases, as confirmed by experimental studies in the model of IL-10 deficient mice, in which spontaneously developed enteritis and administration of recombinant IL-10 showed therapeutic efficacy." (PMID 36289922, 2022). "Low IL-10 release by peripheral T cells was also detected in a group of non-IPEX patients, without detectable FOXP3 mutation, but with autoimmune manifestations of unknown origin (most of them displayed enteritis) kept under control by multiple immunosuppressive treatments." (PMID 21400500, 2011). "Both Que and RU.521 could significantly reduce the protein levels of CXCL10 and TNF-α while increasing the protein levels of IL10 and CCL17 following the induction of enteritis." (PMID 38774206, 2024).
enteritis (continued). "In mice administered butyrate at 80 and 100 mM, expression of Il10 was increased (P ≤ 0.028), and all concentrations of butyrate stimulated an increase (P = 0.049) in Tgfβ expression in mice with and without enteritis." (PMID 28861518, 2017). "During the occurrence of enteritis, the up-regulation of pro-inflammatory cytokines (including IL-6 and TNF-α) acts as a protective inflammatory response and leads to inflammation response through the down-regulation of anti-inflammatory cytokines (including IL-10)." (PMID 40564253, 2025). "Similarly, our findings demonstrated that administration of butyrate at low and high concentrations increased expression of Tgfβ and Il10 in mice with and without enteritis." (PMID 28861518, 2017).
coronary artery disease (53 papers, 2008 to 2026). "This is significant when considering that studies have shown correlative predictive effects for various conditions, such as coronary artery disease and infections associated with burn severities using TNFα/IL-10 ratios." (PMID 38435456, 2024). "Genetic variants in IL-10 have been linked to the development and severity of coronary artery diseases." (PMID 39702436, 2024). "Consistent with this, in a small-scale clinical study of patients with metabolic syndrome (n = 90), higher IL-10 levels were indeed associated with a lower prevalence of severe coronary heart disease." (PMID 39199367, 2024). "Barcelos and colleagues evaluated the association between IL-10 and coronary artery disease in patients suffering from metabolic syndrome." (PMID 38137807, 2023). "In this category of patients, high IL-10 concentrations were associated with a lower incidence of severe coronary artery disease." (PMID 38137807, 2023). "Elevated circulating levels of IL-10 are associated with improved endothelial function in individuals with ongoing systemic inflammation and in coronary artery disease (CAD) patients." (PMID 23691280, 2013). "CCL3, CCL18, CXCL12/SDF-1, CXCL16, IGF1 and IL10 have been linked to pro-angiogenesis and/or coronary artery diseases." (PMID 23496821, 2013). "The 1170 CC genotype weakly predicted increased plasma concentrations of IL-10 in patients (p = 0.04) and in controls (p = 0.03), which was consistent with the modest association of this variant with coronary disease (p = 0.01)." (PMID 17690160, 2008). "In addition, we investigated whether SNPs in the IL-10 gene were associated with coronary disease and with plasma concentrations of IL-10." (PMID 17690160, 2008). "To facilitate preclinical and clinical translation of IL10-based therapeutics for ischemic heart disease, in this study, we addressed the knowledge gap between the therapeutic dosage of IL-10, immune modulation, cardiac repair, and possible unwanted effects." (PMID 39882328, 2024). "The main findings revealed that the comprehensive exercise program conducted over 12 weeks resulted in improved levels of lipid peroxidation MDA, antioxidant enzyme SOD, and anti-inflammatory factor IL-10 in patients with coronary heart disease." (PMID 38827614, 2024). "Other research has found that for coronary artery disease patients with low IL-10/TNF-α ratio has low left ventricular ejection fraction, with high incidence of cardiac related diseases within 10 years." (PMID 32670064, 2020). "The elevated levels of the two inflammatory markers IL-10 and hs CRP are suggestive of potential coronary heart disease risk in the HIV infected patients." (PMID 29387269, 2017). "In agreement, increased circulating IL-10 levels have been reported in obese, T2D, coronary heart disease, and acute coronary syndrome patients." (PMID 28316372, 2017). "Correlations between IL-10 and TC levels as well as differences between IL-10 levels in high and low HDL-C groups indicate a link between inflammatory markers and traditional markers of coronary heart disease risk." (PMID 29387269, 2017). "Along the same line, a reduction in systemic IL-1, IL-6 and increased in IL-10 levels was reported in coronary heart disease patients in response to a 12-week aerobic EXE training program." (PMID 26600018, 2015). "Individuals with increased risk for coronary artery disease presented reduced interleukin-1 (IL-1), IL-6, TNF-α, and C-reactive levels, together with improved IL-10 and transforming growth factor beta-1 systemic levels after an ET program." (PMID 25045207, 2014). "However, in human subjects, IL-10 levels are highly variable, being elevated, decreased, or stationary in patients with stable coronary artery disease or unstable angina, as compared to controls." (PMID 35888173, 2022).
coronary artery disease (continued). "Epicardial adipose tissue expresses and secretes several bioactive molecules including interleukin (IL)-1, IL-1β, IL-6, IL-8, and IL-10, the levels of these interleukins were found as significantly higher in subjects with coronary artery disease when compared to healthy subjects." (PMID 25887962, 2015). "Furthermore, after 12 weeks of aerobic exercise, IL-6 level was found to be decreased while IL-10 level was increased in type 2 diabetic patients and the patients with coronary heart disease." (PMID 24392457, 2013). "Interleukin family was also predicted to be related to coronary artery disease, including IL 6, IL4, IL10, IL1A, and IL1B." (PMID 29861771, 2018). "Increased evidence indicates that decreased IL-10 and TGF-β1 levels are accompanied by the onset of acute coronary syndrome and that high concentrations of IL-10 and TGF-β1 could improve the prognosis of patients with coronary artery disease." (PMID 23285065, 2012). "The crucial link between interleukin-10 and ABO blood groups might explain the impact of the ABO blood groups on clinical outcomes, as inflammatory cascades are critically involved in the pathogenesis of coronary artery disease." (PMID 36836590, 2023).
Hepatic steatosis (53 papers, 2013 to 2025). Steatosis is a term used to denote lipid accumulation within hepatocytes. "They demonstrated an increase in weight change only in HFD-fed Tnfsf14−/− mice, which is also associated with adipocyte hypertrophy and liver steatosis, possibly due to an increase in hepatic lipase and IL-10 together with a decrease in IL-6." (PMID 38255789, 2024). "The IL-10 change in patients with non-alcoholic fatty liver can cause imbalance of intestinal flora." (PMID 35739900, 2022). "In ob/ob and high‐fat diet‐induced obese mice, IL‐6 ameliorated fatty liver by inducing STAT3 phosphorylation, while in IL‐10 knockout mice, deficiency of IL‐6 or STAT3 led to steatosis and hepatocellular injury." (PMID 40066227, 2025). "Homeostatic cholesterol biosynthesis is necessary for immune resolution by CD4+ cells in a c-MAF-AP-1-dependent manner, which drives IL-10 production that was shown to be protective against diet-induced fatty liver disease in mice." (PMID 40510344, 2025). "In NASH, characterized by fatty liver and inflammation, the role of IL-10, a crucial anti-inflammatory cytokine, was explored in mouse models using a liquid diet containing 5% ethanol for 4 weeks or a 12-week HFD." (PMID 38535313, 2024). "Mitoquinone and ASA significantly reduced liver steatosis and inflammation by decreasing the expression of TNFα, IL-6, Serpinb3, and cyclooxygenase 1 and 2 and restoring the anti-inflammatory IL-10." (PMID 37107346, 2023). "Earlier studies have shown that gene silencing of PGC-1α reduced hepatic steatosis but augmented IL10 expression." (PMID 36674967, 2023). "After 12 weeks of treatment, inhibition of interleukin 6 (IL-6), interleukin 10 (IL-10), and C-reactive protein and improvement of hepatic steatosis were observed." (PMID 37111945, 2023). "Through electron microscopy and oil red staining, we found that IL-10 secreted by MSCs can affect liver steatosis induced by hepatectomy." (PMID 33479191, 2021). "IL-10 is an anti-inflammatory cytokine that has a protective role in hepatic steatosis and attenuates hepatocyte damage." (PMID 34025683, 2021). "In contrast, poly I:C-mediated multiple activation of TLR3 in Kupffer cells and hepatic stellate cells (HSCs) attenuates hepatic steatosis and inflammation via IL-10 production." (PMID 32457490, 2020). "Previous studies have revealed that Il-10 can prevent hepatic steatosis and other metabolic abnormalities with anti-inflammatory, immunosuppressive, tolerogenic, and neuroprotective properties." (PMID 31514454, 2019). "Indeed, deletion of Apoa5 in hamsters led to hepatic steatosis even on a chow diet, and Apoa5 knockdown in mice resulted in increased cytokine markers of systemic inflammation, including IL-10, IL-6, and TNF-α." (PMID 41043689, 2025). "HC has been documented to induce fatty liver disease, while high-galactose consumption is associated with severe oxidative stress, senescence, and efflux of pro-inflammatory cytokines, such as TNF-α, IL-6, and IL-10, in the liver." (PMID 41462653, 2025). "Additionally, the PPARγ coactivator 1 α (Pgc-1α), interleukin-6 (Il-6), and interleukin-10 (Il-10) gene expression were augmented, while hepatic steatosis decreased and liver parenchyma was recovered." (PMID 35326098, 2022). "Moreover, among adipokines, adiponectin in humans and rodents contributes to not only the oxidization of fatty acids in hepatocytes but also the reduction in TNF-α and IL-10 production in Kupffer cells, thereby alleviating liver steatosis and inflammation." (PMID 32457490, 2020). "For example, dietary supplementation with whole walnuts resulted in a significant decrease in macrophage infiltration and suppression of pro-inflammatory gene expression (tumor necrosis factor; TNF-α, interleukin-6; IL-6 and IL-10) in a mouse model of high-fat diet (HFD)-induced fatty liver disease." (PMID 31137456, 2019).
Hepatic steatosis (continued). "Whether this decrease in Il10 expression is truly T cell dependent or whether it is due to the less advanced stage of hepatic steatosis in Lck-Cre Atg7f/f mice remains to be determined." (PMID 30619297, 2018). "In addition, inhibition of hepatic tissue necrotic factor a (TNFα) improves steatosis in ob/ob mice, and decreasing the expression of interleukin-10 (IL-10) derived from Kupffer cells can improve hepatic steatosis." (PMID 25672270, 2015). "On the other hand, IL-10 may act as a protective factor against the development of NAFLD being higher in a subgroup of obese children with steatohepatitis as compared to obese children free of NAFLD or those with simple fatty liver." (PMID 38535313, 2024). "Given that inactivation of Kupffer with gadolinium chloride prevents ethanol-induced fatty liver disease in rats, any reduction in the efficacy of adiponectin to promote IL-10 and reduce TNFα could promote the fatty liver phenotype afflicting dolphins with iron overload." (PMID 24065958, 2013). "In mice with long-term EC-12 consumption, we observed reductions in hepatic steatosis and serum MCP-1 levels and increases in serum IL-6 and IL-10 levels compared to the findings in the control group (Experiment 2)." (PMID 38999780, 2024). "↓BWG, FBG, insulin, HOMA-IR value, serum LPS, hepatic steatosis, adipocyte hypertrophy; ↑HDL-C level; ↓Ileum IL-6 and TNF-α levels; ↑↓Ileum IL-10 levels." (PMID 37396125, 2023). "Serum IL-10 levels are significantly lower in patients with NASH, while IL-17 exacerbates hepatic steatosis and inflammation in NAFLD." (PMID 35392825, 2022). "The strong correlation observed between FRAP and IL10/TNF ratio in LPHs-treated mice re-enforces the interplay between the oxidative stress and inflammation in the context of fatty liver disease." (PMID 34439470, 2021). "Similar to the previously observed protective role for AhR against hepatic steatosis and hepatic inflammation in HFD mice, indigo supplementation decreased liver triglyceride content and hepatic inflammation by increasing IL-10 and M2-like macrophages." (PMID 30944419, 2019). "Our results demonstrate a direct connection with the lower expression of pro-inflammatory IL-6 and increase of anti-inflammatory IL-10, and lower values of AST with the reduction of hepatic steatosis." (PMID 31861497, 2019). "In this study, KMUP-1 increased IL-10 and decreased MMP-9 significantly, little affected TNFα, indicating its anti-inflammatory properties in hepatic steatosis." (PMID 27548140, 2016). "IL-10 is one of the most important anti-inflammatory cytokines; it inhibits TNF-α and LPS in Kupffer cells, thereby ameliorating ALD and preventing liver steatosis." (PMID 25692549, 2015). "Accordingly, in the present study we have shown that both increased levels of Il12a, Il12b, Il18, Ifng, Tnfa, and Il10 mRNA expression seen in the liver of HFH fed mice and hepatic steatosis were reduced in HFL fed mice." (PMID 25251155, 2014). "Compared to controls, AAA-1-immunized mice showed higher plasma CK-18 (5.3 vs. 2.1 pg/mL, p = 0.031), IL-6 (13 vs. 6.9 pg/mL, p = 0.035), IL-10 (27.3 vs. 9.8 pg/mL, p = 0.007), TNF-α (32.1 vs. 24.2 pg/mL, p = 0.032), and liver steatosis (93.4% vs. 73.8%, p = 0.007)." (PMID 39595946, 2024). "Although it has been suggested that IL‐10 in the liver can inhibit TNFα production and protect against hepatic steatosis during HFD, no improvement in insulin sensitivity has been found." (PMID 36637998, 2023). "Our data indicate that IL-10 is not involved in the development of liver steatosis or the effect of soy protein on liver steatosis in obese Zucker rats." (PMID 38075211, 2023). "In fact, IL-10−/− mice fed with an HFD present more hTG content in comparison to the wild type group, while IFNα receptor 1 or TNFα receptor 1 knockouts mice fed with hyperlipidemic diets show an attenuated hepatic steatosis." (PMID 34439470, 2021).
Hepatic steatosis (continued). "In turn, rTFA intake reduced the levels of the anti-inflammatory cytokine IL-10 in blood serum, as well as hepatic steatosis, without, however, impacting greater body weight gain in rats." (PMID 34556715, 2021). "The absence of CCR7 decreases IL-10-producing iNKT cells in fatty liver, and exacerbates NAFLD." (PMID 33853536, 2021). "IL-10 treatment also apparently exacerbated alcoholic liver steatosis, but not liver injury, suggesting that exogenous IL-10 may exert systemic anti-inflammatory roles and suppress the protective function of NK cells against alcohol-induced fatty liver." (PMID 29163491, 2017).